TBX6 (T-box transcription factor 6)
Description:
T-box transcription factor that plays an essential role in the determination of the fate of axial stem cells: neural vs mesodermal. Acts in part by down-regulating, a specific enhancer (N1) of SOX2, to inhibit neural development. Seems to play also an essential role in left/right axis determination and acts through effects on Notch signaling around the node as well as through an effect on the morphology and motility of the nodal cilia (By similarity).
Synonyms: SCDO5
Tractability: No criterion of Open Targets' tractability assessment is met for any kind of drug.
Gene: Protein-coding gene on chromosome 16 (30,085,793 to 30,091,933, reverse strand). Ensembl gene ENSG00000149922.
Subcellular location: Nucleus
Subcellular location (Human Protein Atlas): Nucleoplasm
Pathways (Reactome):
Developmental Biology: Formation of paraxial mesoderm; Formation of the posterior neural plate; Somitogenesis
Gene Ontology:
Molecular function: DNA binding; DNA-binding transcription activator activity; protein binding; sequence-specific double-stranded DNA binding; DNA-binding transcription factor activity, RNA polymerase II-specific; RNA polymerase II cis-regulatory region sequence-specific DNA binding; RNA polymerase II-specific DNA-binding transcription factor binding; transcription corepressor activity; DNA-binding transcription factor activity
Biological process: anatomical structure morphogenesis; cell fate specification; mesoderm development; negative regulation of transcription by RNA polymerase II; regulation of transcription by RNA polymerase II; positive regulation of DNA-templated transcription; regulation of DNA-templated transcription
Cellular component: chromatin; nucleus
Genetic constraint (gnomAD): Loss-of-function variants: 29 observed, 42.22 expected, observed/expected ratio (o/e) 0.69, 90% interval 0.51 to 0.94. The upper end of that interval is the gene's LOEUF score, 0.94, which puts it in group 3 of 6, group 1 being the genes least tolerant of losing a copy. Missense variants: 569 observed, 601.97 expected, observed/expected ratio (o/e) 0.95, 90% interval 0.88 to 1.01. Synonymous variants: 249 observed, 242.7 expected, observed/expected ratio (o/e) 1.03, 90% interval 0.92 to 1.14.
Homologues: Orthologues: macaque TBX6 (95% identical), chimpanzee TBX6 (94% identical), rabbit TBX6 (91% identical), dog TBX6 (90% identical), pig TBX6 (90% identical), guinea pig TBX6 (89% identical), mouse Tbx6 (88% identical), rat Tbx6 (87% identical), tropical clawed frog tbx6 (46% identical), zebrafish tbx6 (42% identical), Drosophila melanogaster Doc3 (29% identical), Drosophila melanogaster Doc2 (29% identical), and 12 more. Paralogues in human: MGA (34% identical), TBX2 (33% identical), TBX15 (32% identical), TBX18 (32% identical), TBX3 (31% identical), TBX1 (31% identical), TBX4 (30% identical), TBX5 (30% identical), TBX10 (29% identical), TBX22 (29% identical), TBX20 (29% identical), TBR1 (28% identical), and 4 more.
Diseases named in the same sentence as TBX6 in open-access papers:
TBX6 is named in the same sentence as 43 diseases in open-access papers, as found by Europe PMC text mining. Sharing a sentence is not in itself a finding about the gene and the disease. The quoted sentences say what the papers report.
scoliosis (19 papers, 2015 to 2025). A congenital or acquired spinal deformity characterized by lateral curvature of the spine. "The genetic basis of congenital scoliosis is complex, involving mutations in multiple genes, particularly those related to the Notch signaling pathway, such as TBX6 and LFNG." (PMID 40980134, 2025). "Congenital scoliosis is largely characterized by mutations in developmental genes such as TBX6, DLL3, and MESP2 and components of the Notch, Wnt, and HOX pathways." (PMID 41153437, 2025). "Similar expectations, empirical modeling and observations for Tbx6-derived scoliosis, i.e., TBX6-associated congenital scoliosis in mice, were found." (PMID 36180924, 2022). "This identified 12 CNVs in four scoliosis-associated genes (TBX6, NOTCH2, DSCAM, and SNTG1) as well as eight recessive and 64 novel rare CNVs in 15 additional genes." (PMID 34440387, 2021). "In contrast, loss of Tbx6 function greatly increased the chance of an animal developing scoliosis with age." (PMID 32979261, 2020). "The higher scoliosis incidence in the her1-/-; her7-/-; tbx6-/- mutants is probably due to the muscle defects caused by the loss of Tbx6 activity." (PMID 32979261, 2020). "Studies have reported that the polymorphism of the TBX6 gene is associated with hemivertebra and scoliosis in the Chinese Han population; two in four cases in our study showed hemivertebra, consistent with the phenotype." (PMID 31391865, 2019). "Thus, perturbation of myogenesis due to loss of Tbx6 function, combined with mutations in her1 and her7, results in long lasting muscle phenotypes that appear to be correlated with scoliosis." (PMID 32979261, 2020). "The patients with the heterozygous TBX6 mutation exhibited segmental congenital vertebral malformations including hemivertebrae and fused vertebral blocks, which resulted in short stature and scoliosis." (PMID 26090680, 2015). "Thus we indicated regulation of the two mesp genes with different weights by Notch signaling and Tbx6 in our network of somitogenesis controlled by scoliosis-linked genes with the input of the segmentation clock and its intrinsic feedback as an autoinhibitory loop at the level of her." (PMID 30711748, 2019). "Alternatively, rare protein-coding variants can provide insights into gene functionality, as exemplified for PRRT2 and TBX6, the genes associated with PKD304 and scoliosis, respectively." (PMID 39332410, 2024). "Among the genes that have been confirmed to be involved in the development of scoliosis in humans (TBX6, FGF3, LBX1, POC5, TTLL1) and vertebrates (Kif6 and Ptk), several are ciliary genes." (PMID 37239471, 2023). "TBX6 at 16p11.2, which has a role in bone development and scoliosis, has pathologic fracture of vertebrae in its top 1% phenome associations (P = 0.0028)." (PMID 34715901, 2021). "By 12 months 88% (6/7) first generation tbx6-/- animals had developed scoliosis; this corresponds exactly to the proportion of individuals from these two mutant populations that present vertebrae defects." (PMID 32979261, 2020). "At three months post fertilization 11 out of 35 (31.4%) tbx6-/- third generation animals developed scoliosis, similar to first generation animals 3 out of 8 (38%) evaluated at a similar age." (PMID 32979261, 2020). "By the end of the experiment (12 months post fertilization) all her1-/-; her7-/-; tbx6-/- first generation animals (8/8) had developed scoliosis." (PMID 32979261, 2020). "At the same time point, 8 out of 38 (21%) her1-/-; her7-/-; tbx6-/- third generation animals presented scoliosis in contrast to first generation animals 5 out of 8 (63%)." (PMID 32979261, 2020). "In contrast tbx6-/- mutants with scoliosis showed a smaller muscle volume at all anterior positions compared to non-scoliotic tbx6/- mutant animals." (PMID 32979261, 2020).
scoliosis (continued). "In summary, we have shown that the zebrafish mutants for her1-/-; her7-/-, tbx6-/- and triple her1-/-; her7-/-; tbx6-/- can serve as a model for adult scoliosis, because they reproduce the muscle and bone indicators present in clinical patients." (PMID 32979261, 2020). "In contrast, her1-/-; her7-/-; tbx6-/- mutant animals showed a lower muscle volume in regions in which scoliosis was observed and also had perturbed slow and fast muscle development." (PMID 32979261, 2020). "TBX6 is currently involved in 16p11.2 recurrent deletion syndrome and is highly correlated with scoliosis if there was a presence of a hemizygous T-C-A haplotype." (PMID 31475041, 2019). "Similarly, in the third generation, all animals (7/7) her1-/-; her7-/-; tbx6-/- animals developed scoliosis at 14 months post fertilization." (PMID 32979261, 2020). "Unfortunately, no information about the muscles of scoliosis patients with mutations in TBX6 is available for comparison." (PMID 32979261, 2020). "There are three common SNPs at TBX6 contributing to scoliosis (primarily in individuals who have additional disruptive mutations at the gene), and one was identified as an eQTL in our approach; perhaps an even stronger signal could have been observed if all three were included." (PMID 34715901, 2021). "Furthermore, the hemivertebra and scoliosis resulted from the nonfunctional allele in combination with another common hypomorphic allele haplotype T-C-A (three common single nucleotide polymorphisms: rs2289292, rs3809624, rs3809627) in TBX6." (PMID 36140791, 2022). "The only tbx6-/- mutant individual in this study that did not develop scoliosis had higher muscle mass than its scoliotic siblings (similar levels than the wild type and the her1-/-; her7 -/-) implying that muscle mass and scoliosis are directly correlated." (PMID 32979261, 2020).
spondylocostal dysostosis (9 papers, 2013 to 2024). Spondylocostal dysplasia is a rare genetic disorder characterized by defects of the bones of the spine (vertebrae) and abnormalities of the ribs. "According to the OMIM database, the heterozygous or compound heterozygous mutations in the TBX6 gene would cause spondylocostal dysostosis (SCDO5), characterized by developmental vertebral and rib defects." (PMID 39039444, 2024). "Two cases of spondylocostal dysostosis 5 had mutations in TBX6 gene but the significance of the identified variants is partly unclear." (PMID 35611473, 2022). "This is the first case report of spondylocostal dysostosis and brachydactyly associated with TBX6 and IHH variants." (PMID 35846898, 2022). "Development is also sensitive to Tbx6 levels; spondylocostal dysostosis in humans can be caused by mutations in TBX6 that reduce its transcriptional activity." (PMID 32855167, 2020). "It has been reported that a dominant type of familial spondylocostal dysostosis is caused by a mutation that affects the transcriptional activity of TBX6 with respect to Notch signaling." (PMID 26090680, 2015). "Taking into account of the similar congenital vertebral malformations, we surmised that the vertebral anomalies of Tbx6Oune/+ rats and spondylocostal dysostosis caused by the stoploss TBX6 mutation would share a common molecular mechanism." (PMID 26090680, 2015). "Recently, a missense mutation in the last codon of the TBX6 transcript was observed in a Macedonian family with the autosomal dominant form of spondylocostal dysostosis (SCD), characterized by segmentation defects of the vertebrae." (PMID 23954021, 2013). "In humans, these heterozygous conditions can lead to syndromes, including Holt-Oram Syndrome (HOS, TBX5), ulna mammary syndrome (UMS, TBX3), DiGeorge syndrome (TBX1), spondylocostal dysostosis (TBX6) and cleft palate and ankyloglossia (TBX22)." (PMID 32855167, 2020).
hemivertebra (4 papers, 2019 to 2022). "Thus, our results indicated that hemivertebrae caused by the compound inheritance of TBX6 can be corrected effectively by hemivertebra resection combined with segmental fusion—a finding that may reassure CS children and their parents." (PMID 36035411, 2022).
MRKH syndrome (4 papers, 2018 to 2023). "A number of studies aimed to investigate the genetic causes of MRKH syndrome, focusing on CNVs and candidate genes involving TBX6, AMH, LHX1, WNT, and HOX." (PMID 37789575, 2023). "By analysing candidate genes, being located in these aberrations, mutations in genes such as LHX1, RBM8A and TBX6 have been identified as being causative of MRKH syndrome." (PMID 29527097, 2018). "In a patient affected by MRKH type II, we identified a chromosomal deletion including TBX6, a candidate gene for MRKH syndrome already described in the literature as deleted in other 9 cases of this syndrome." (PMID 33432050, 2021). "In cases of MRKH syndrome, recurrent microdeletions and microduplications (1q21,1; 2q12.1q14.1; 16p11.2; 17p14.3; 17q12; 22q11.21; 22q11.21q11.23) and mutations in genes located on these loci (RBM8A, PAX8, TBX1, TBX6, LHX, HNF1B, WNT4) have been identified." (PMID 33883018, 2021). "Studies conducted on mouse models showed that lack of TBX6 leads to vertebral and rib anomalies together with urogenital malformations, features often associated to MRKH syndrome." (PMID 33432050, 2021).
autism spectrum disorder (2 papers, 2021 to 2022). A spectrum of developmental disorders that includes autism, and Asperger syndrome. "Two cases with 16p11.2 (proximal, BP4–BP5) and clinical features associated with 16p11.2 (TBX6) proximal region deletion may include developmental delay, cognitive impairment, language delay, autism spectrum disorder, neurologic issues including seizures, or electroencephalogram abnormalities." (PMID 34285689, 2021).
breast carcinoma (2 papers, 2013 to 2015). "p.N212delN, which was identified in three cases of breast cancer, affects a position that is largely conserved, only TBX6 showing a deviating serine." (PMID 26579496, 2015).
epilepsy (2 papers, 2021 to 2024). A brain disorder characterized by episodes of abnormally increased neuronal discharge resulting in transient episodes of sensory or motor neurological dysfunction, or psychic dysfunction. "TBX6 has been associated with vertebral malformations and PRRT2 has been associated with epilepsy and paroxysmal dyskinesia." (PMID 39202413, 2024).
Mayer-Rokitansky-Küster-Hauser syndrome (2 papers, 2021 to 2024). "TBX6 has been implicated as a candidate gene for another associated clinical manifestation of microdeletions at 16p11.2 which leads to a complete absence, or underdevelopment, of the female reproductive system (with Mayer-Rokitansky-Küster-Hauser syndrome [MRKH; MIM: 277000])." (PMID 39495297, 2024).
Müllerian aplasia (2 papers, 2013 to 2023). "We report here the results of genetic studies on Müllerian aplasia, namely, results of TBX6 and LHX1 mutation screening in 112 MA patients and CNV analysis in a subset of them." (PMID 23954021, 2013). "It is also reported carrying variants in both TBX6 and LHX1 or a CNV in combination with TBX6 variants might play a role in the etiology of Mullerian aplasia." (PMID 37789575, 2023).
spondylocostal dysostosis 5 (2 papers, 2022 to 2024). Any spondylocostal dysostosis in which the cause of the disease is a mutation in the TBX6 gene. "Deleterious homozygote or compound heterozygote mutations in the TBX6 gene could lead to spondylocostal dysostosis 5 [online mendelian inheritance in man (OMIM) 122600]." (PMID 36035411, 2022). "Patients with TBX6-related spondylocostal dysostosis 5 present with rib deformities and a short trunk, which is caused by extensive vertebral deformities such as hemivertebrae, butterfly vertebrae, and vertebral fusion." (PMID 36035411, 2022).
autism (1 paper, 2011). Persistent deficits in social interaction and communication and interaction as well as a markedly restricted repertoire of activity and interest as well as repetitive patterns of behavior. "In addition the autism-associated proximal 16p11.2 deletion (TBX6) was observed in approximately 1% (3/336) of all autism cases analyzed." (PMID 22102821, 2011).
ciliopathy (1 paper, 2022). A genetic disorder of the cellular cilia or the cilia anchoring structures, the basal bodies, or of ciliary function. "The targets of CREBP1 found from among the genes shared between the HLHS and ciliopathy interactomes were EP300, PRNP, SMAD3, SUMO1 and TBX6, while the targets of ALX4 were JUN and TCF7L2." (PMID 35456433, 2022).
DiGeorge syndrome (1 paper, 2016). "Various promising CNVs have been reported located at 1q21.1 (RBM8A), 16p11.2 (TBX6), 17q12 (LHX1, HNF1B), as well as 22q11 associated with DiGeorge syndrome." (PMID 28003020, 2016).
endometrial tumour (1 paper, 2024). "Interestingly, the transcription factor TBX6 is expressed at low levels in normal endometrial tissue but a correlation between TBX6 gene dosage and expression was identified in endometrial tumour tissue." (PMID 39495297, 2024).
kidney malformations (1 paper, 2025). "The T-C-A haplotype, when in trans with a loss-of-function TBX6 variant, is associated with congenital scoliosis and more recently kidney malformations." (PMID 40597352, 2025).
lung disease (1 paper, 2022). "This compound inheritance model has been demonstrated at the RBM8A-1q21.1 locus in association with the TAR syndrome, the TBX6-16p11.2 locus in association with congenital scoliosis, the F12-5q35 Sotos deletion locus in association with blood clotting, and the TBX4-FGF10 lung disease." (PMID 36180924, 2022).
orofacial cleft (1 paper, 2020). A disorder of facial skeleton that is characterized by cleft lip and/or cleft palate that result in feeding, speech and hearing problems caused by failures during development. "Although TBX6 is considered to be a key gene resulting in several major phenotypes in 16p11.2 duplication, potential genes associated with orofacial cleft in this region still require further exploration." (PMID 32863884, 2020).
pulmonary atresia (1 paper, 2025). "TBX6 disruption has been associated with skeletal defects, while a deletion in the genomic locus that also contains TBX6 has been associated with pulmonary atresia with ventricular septal defect, a severe form of Tetralogy of Fallot in humans, along with other candidate genes." (PMID 41153848, 2025).
situs inversus (1 paper, 2025). A congenital condition in which there is complete right-to-left reversal of the position of the major thoracic and abdominal organs (that is, they are arranged in a mirror image of the normal positioning). "However, polydactyly and situs inversus have not been associated with this condition, although interestingly heterotaxy has been observed in TBX6 knockout mice embryos." (PMID 40597352, 2025).
cancer (2 papers, 2021 to 2022). A tumor composed of atypical neoplastic, often pleomorphic cells that invade other tissues. "The induction of T, Eomes, Tbx6 and Lef1, among other genes, points towards increased WNT pathway activity in hypoxia, which was previously observed in cancer cells and linked to EMT." (PMID 36102628, 2022).
skeletal dysplasia (2 papers, 2022 to 2025). Any Mendelian diseases that affects growth and development of the skeleton. "The DNA sequence analysis [Invitae Skeletal Dysplasia Panel] identified variants in TBX6 and IHH, which probably correlate with our patient's distinct phenotypes." (PMID 35846898, 2022). "Analogous patterns are well recognized in other genetic conditions such as COL2A1 (Collagen, Type II, Alpha-1)-related skeletal dysplasias and TBX6 (T-Box Transcription Factor 6)-related segmentation defects, where allelic heterogeneity and modifiers account for wide phenotypic variability." (PMID 41300719, 2025).
TBX6 also shares sentences with these, for which no sentence is quoted: Cognitive impairment (2 papers); developmental delay (2); language delay (2); brachydactyly (1); cardiac hypertrophy (1); Chiari malformation type II (1); dysostosis (1); genetic disorder (1); Holt-Oram syndrome (1); infection (1); Kyphoscoliosis (1); myopia (1); neurological disease (1); paroxysmal dyskinesia (1); Phelan-McDermid syndrome (1); renal agenesis (1); Sotos syndrome (1); Tetralogy of Fallot (1); Thrombocytopenia (1); tumor (1); ventricular septal defect (1); Williams syndrome (1).